HOXA10 (homeobox A10)
Description:
Sequence-specific transcription factor which is part of a developmental regulatory system that provides cells with specific positional identities on the anterior-posterior axis. Binds to the DNA sequence 5'-AA[AT]TTTTATTAC-3'.
Synonyms: HOX1H; HOX1; HOX1.8; PL
Tractability: PROTAC: ubiquitination databases record sites on it.
Gene: Protein-coding gene on chromosome 7 (27,170,605 to 27,180,261, reverse strand). Ensembl gene ENSG00000253293.
Subcellular location: Nucleus
Subcellular location (Human Protein Atlas): Nucleoplasm; Nuclear bodies
Gene Ontology:
Molecular function: DNA-binding transcription activator activity, RNA polymerase II-specific; histone deacetylase binding; protein binding; RNA polymerase II cis-regulatory region sequence-specific DNA binding; sequence-specific double-stranded DNA binding; DNA-binding transcription factor activity, RNA polymerase II-specific; DNA binding
Biological process: positive regulation of transcription by RNA polymerase II; regulation of transcription by RNA polymerase II; spermatogenesis; prostate gland development; regulation of DNA-templated transcription; response to estrogen; response to testosterone
Cellular component: cytoplasm; nuclear body; nucleoplasm; nucleus; chromatin; transcription regulator complex
Genetic constraint (gnomAD): Loss-of-function variants: 12 observed, 23.31 expected, observed/expected ratio (o/e) 0.51, 90% interval 0.33 to 0.83. The synonymous counts are far from expectation, so gnomAD's model fits this gene poorly and the ratio says little. Missense variants: 656 observed, 536.89 expected, observed/expected ratio (o/e) 1.22, 90% interval 1.14 to 1.3. Synonymous variants: 327 observed, 249.44 expected, observed/expected ratio (o/e) 1.31, 90% interval 1.2 to 1.44.
Homologues: Orthologues: chimpanzee HOXA10 (99% identical), macaque HOXA10 (96% identical), dog HOXA10 (96% identical), rabbit HOXA10 (95% identical), pig HOXA10 (95% identical), mouse Hoxa10 (91% identical), rat Hoxa10 (91% identical). Paralogues in human: HOXD10 (40% identical), HOXC10 (35% identical), HOXC9 (24% identical), HOXD9 (24% identical), HOXB9 (21% identical), HOXC12 (18% identical), HOXA4 (16% identical), HOXD4 (16% identical), HOXD12 (16% identical), HOXA5 (16% identical), HOXC11 (16% identical), HOXC4 (16% identical), and 30 more.
Diseases named in the same sentence as HOXA10 in open-access papers:
HOXA10 is named in the same sentence as 125 diseases in open-access papers, as found by Europe PMC text mining. Sharing a sentence is not in itself a finding about the gene and the disease. The quoted sentences say what the papers report.
endometriosis (96 papers, 2006 to 2026). The growth of functional endometrial tissue in anatomic sites outside the uterine body. "Upregulation of particular miRNAs, notably miR-135a and miR-135b, has been found to directly inhibit HOXA10 expression in women with recurrent implantation failure (RIF) or endometriosis-associated infertility." (PMID 40427016, 2025). "Research on HOXA10’s function in endometriosis is necessary, though, as the mechanisms underlying the development of ectopic endometrium are still poorly understood." (PMID 40305321, 2025). "Crucial molecules implicated in implantation, including integrin αVβ3 and HOXA10, are diminished in individuals with endometriosis." (PMID 39866586, 2024). "Diminished HOXA10 expression can impair uterine receptivity and is implicated in decreased implantation associated with endometriosis, PCOS, and leiomyomas." (PMID 39796491, 2024). "Studies have shown that miR-135a/b is upregulated in the proliferative phase in patients with endometriosis-related infertility causing repression of the transcription factor HOXA-10." (PMID 38813329, 2024). "For example, miRNA-135a/b, regulating HOXA10, is upregulated in endometriosis and cause progesterone resistance." (PMID 36901685, 2023). "Testosterone is a controller of HOXA10 expression, which is a key player in the development of the female reproductive tract, and has been implicated in endometriosis." (PMID 38049874, 2023). "The downregulation of HOXA10 expression has been reported to be caused by DNA hypermethylation in endometriosis and endometrial cancer." (PMID 36834456, 2023). "As promoter hypermethylation is generally associated with gene silencing, the reduced HOXA10 gene expression in the endometrium of women with endometriosis is, at least in part, responsible for the impaired uterine receptivity." (PMID 36387918, 2022). "Among transcription factors responsible for uterine function, HOXA10 is widely known to be associated with endometrial receptivity and progesterone receptor expression, and is hypermethylated in patients with endometriosis." (PMID 36359004, 2022). "Abnormal HOXA10 expression during the luteal phase usually associates with endometriosis, RIF and miscarriage." (PMID 33201593, 2021). "Remarkably, HOXA10 mutant mice are infertile and show a diminished decidualization response, while low HOXA10 levels in humans are associated with endometriosis, which is partly due to an up-regulation in miR-135b levels." (PMID 22911744, 2012). "The HOXA10 promoter is also susceptible to methylation in the endometria of women wearing intrauterine devices, in patients with ovarian cancer or endometriosis, and in the uteri of mice exposed to diethylstilbestrol." (PMID 23028963, 2012). "We observed a progressive, statistically significant loss of HOXA10 mRNA and protein throughout the progression of endometriosis from three to 15 months." (PMID 17118171, 2006). "Furthermore, dysregulation of p300/CREB-binding protein-associated factor (PCAF) impairs HOXA10-mediated gene regulation through altered acetylation patterns in the eutopic endometrium of women with endometriosis." (PMID 40072055, 2025). "Regarding the reproductive system, HOXA10 plays a vital role in uterine development and endometrial receptivity, which is crucial for implantation, as aberrant HOXA10 expression is linked to infertility and endometriosis." (PMID 40305321, 2025). "In the context of endometriosis, altered expression of HOXA10 has been shown to be associated with reduced endometrial receptivity and ectopic lesion development, indicating a potential functional role in endometriosis for hsa-mir-135a in regulating this gene." (PMID 36009038, 2022). "Based on mouse comparative studies, it was suggested that impaired endometrial receptivity in the endometriosis group may be caused by altered gene expression due to methylation of the homeobox protein A10 (HOXA10) and A11 (HOXA11)." (PMID 33411206, 2021).
endometriosis (continued). "We suggest that decreased expression of HOXA10/HOXA11 in endometrial stromal cells may be a causal factor in the development of endometriosis." (PMID 32850789, 2020). "Aberrant expression of epigenetic alterations in endometriosis include genomic DNA methylation of the gene encoding progesterone receptor-β, HOXA10, ESR2, which are candidate genes responsible for the development of progesterone resistance and implantation failure." (PMID 32658928, 2020). "HOXA10 may also be involved in this process since its expression is reduced in endometriosis, and in vitro experiments implicated it in the regulation of FKBP52." (PMID 31387263, 2019). "In a United States GWA study, SNP-association with endometriosis was reported with LD blocks near nuclear factor erythroid-derived 2-like 3 gene, typically expressed in placenta, and HOXA10 and HOXA11 genes, two candidate genes of the homeobox A transcription factors family." (PMID 31717614, 2019). "The promoter region of HOXA10 gene was found to be hypermethylated in the eutopic endometrium of women with endometriosis and may be a cause of HOXA10 downregulation." (PMID 24927773, 2014). "Of interest, the hypermethylation of the HOXA10 gene promoter, which means gene silencing, is consistent with studies reporting that HOXA10 levels are reduced in the eutopic endometrium of women affected by endometriosis, which may be a cause of the impaired fertility of these women." (PMID 31717614, 2019). "The impaired expression of HOXA10 and prokineticins is associated with conditions like unexplained infertility, PCOS, endometriosis, and recurrent pregnancy loss." (PMID 39915377, 2025). "Studies have observed that HOXA10 gene expression is significantly downregulated in the endometrium of women with both adenomyosis and endometriosis." (PMID 41374450, 2025). "It has been demonstrated that hypermethylation of HOXA10 plays a crucial role in endometriosis and implantation failure in women undergoing in vitro fertilization treatment." (PMID 40792071, 2025). "Further studies to evaluate the expression pattern of HOXA10/HOXA11 allowed for the presentation of DNA methylation as a possible mechanism of altered gene expression in endometriosis." (PMID 41153447, 2025). "In a baboon model of surgically induced endometriosis, complete and partial methylation in the F1 region of the HOXA10 promoter was found in the eutopic endometrium." (PMID 39858500, 2025). "Several studies have revealed that the level of HOXA10 methylation is significantly higher in the endometrial tissue of women with endometriosis." (PMID 40792071, 2025). "Women with endometriosis have methylated HOXA10 in their endometrium during the secretory phase; methylation patterns are similar in all populations." (PMID 40305321, 2025). "Whereas in endometriosis patients, HOXA10 methylation levels increase during the secretory phase, resulting in low HOXA10 expression levels, and thereby cell differentiation inhibition in the eutopic endometrium." (PMID 40792071, 2025). "They revealed that the level of HOXA10 methylation is considerably higher in eutopic endometrium collected during the secretory phase in patients with endometriosis." (PMID 40792071, 2025). "ChIP analysis of endometriotic lesions showed hypoacetylation of H3/H4 around promoter regions of genes previously demonstrated to be downregulated in endometriosis, such as HOXA10, ESR1, CDH1, and CDKN1A, compared with disease-free endometrium." (PMID 40590223, 2025). "HOXA10, a key regulator of uterine development and endometrial differentiation, shows altered expression in endometriosis." (PMID 40072055, 2025). "Several types of endometriosis, including superficial peritoneal (SE), ovarian (OE), and deep infiltrating endometriosis (DE), have lower HOXA10 expression in both eutopic and ectopic endometrial tissues." (PMID 40305321, 2025).
endometriosis (continued). "Concerning hypermethylation, the most studied gene is HOXA10 and several studies have shown the link between its hypermethylation and endometriosis." (PMID 40792071, 2025). "Patients with endometriosis have decreased expression of HOXA10 in the eutopic endometrium during the secretory phase." (PMID 40792071, 2025). "Endometrial polyps (EPs), endometriosis, polycystic ovarian syndrome (PCOS), leiomyoma, and hydrosalpinx are associated with both the altered expression of HOXA10 and HOXA11 and infertility." (PMID 40305321, 2025). "This review highlights the molecular underpinnings of HOXA10/HOXA11 in reproductive health and their dysregulation in benign pathologies associated with infertility, such as endometriosis, adenomyosis, and endometrial polyps." (PMID 40305321, 2025). "The dysregulation of HOXA genes, particularly HOXA10 and HOXA11, plays a crucial role in the pathophysiology of several uterine conditions associated with female infertility, such as EPs, endometriosis, and leiomyomas." (PMID 40305321, 2025). "HOXA10 hypermethylation was demonstrated as a mechanism for decreased HOXA10 expression in the endometrium of women with endometriosis." (PMID 40590223, 2025). "This sheds light on the intricate hypermethylation profile of HOXA10 gene, negatively regulating HOXA10 expression and contributing to the heterogeneity of endometriosis." (PMID 40792071, 2025). "For instance, the mean methylation rate of HOXA10 in the eutopic endometrium from women with endometriosis varied between 4 and 70% depending on the gene regions analyzed; F1-3 regions of the HOXA10 promoter, as well as the 5′untranslated region (5′UTR)." (PMID 39858500, 2025). "For example, miR-135b, which is frequently high in women with RIF or endometriosis, directly targets HOXA10, a transcription factor required for stromal cell differentiation and epithelial transition during the window of implantation." (PMID 40427016, 2025). "For instance, reduced HOXA10 expression in endometriosis stems from hypermethylation and chronic inflammation, disrupting immune modulation and cytokine signaling." (PMID 40305321, 2025). "The HOXA10 and HOXA11 genes regulating in-uterine embryogenesis and the regulation of ER are involved in the pathogenesis of infertility associated with endometriosis." (PMID 41153447, 2025). "Determining the levels of HOXA10 methylation is essential for creating targeted DNA demethylation treatments for endometriosis." (PMID 40305321, 2025). "HOXA10 expression is normally upregulated by progesterone in the endometrium to promote receptivity, but in endometriosis, its expression is restricted by promoter methylation, potentially contributing to implantation failure." (PMID 41009686, 2025). "It has been demonstrated that homeobox 10A (HOXA10) expression is reduced in women with endometriosis compared to healthy controls." (PMID 40362218, 2025). "The HOXA10 gene, which is essential for endometrial receptivity and implantation, was discovered to be hypermethylated in endometriosis patients." (PMID 39311136, 2024). "Hypermethylation in the HOXA10 promoter region, which is required for endometrial receptivity and implantation, reduces expression and contributes to endometriosis and infertility." (PMID 39311136, 2024). "For instance, in human endometriosis research, inhibition of HOXA10 expression led to enhanced proliferation, migration, and invasion of hEM15A cells by upregulating miR-27b-3p expression." (PMID 39409719, 2024). "As a representative example, high methylation of the HOXA10 gene promoter in the endometrium of women with endometriosis leads to gene silencing, resulting in decreased levels of HOXA10 in the ectopic endometrium, potentially impairing female fertility." (PMID 39345884, 2024). "This study concluded that HOXA-10 gene expression in the eutopic endometrium samples of women with endometriosis is significantly downregulated compared to the eutopic endometrium samples of control cases." (PMID 38813329, 2024).
endometriosis (continued). "Our gathered evidence was classified as high-quality studies, and we found a higher HOXA10 DNA methylation level in the endometrium tissue of women with endometriosis in all the included studies." (PMID 36979165, 2023). "From 491 retrieved studies, five original articles investigating the DNA methylation level of HOXA10 from endometrium tissues among endometriosis women were included." (PMID 36979165, 2023). "Measuring the expression of the HOXA10 gene in women is clinically essential to predicting endometriosis, endometrial receptivity, and the development of pinopodes in the endometrium during the luteal phase." (PMID 37629050, 2023). "The secretory phase was identified as the best sampling time for HOXA10 DNA methylation study in endometriosis, and the most studied DNA methylation site is the promoter region of the HOXA10." (PMID 36979165, 2023). "Changes in methylation of the Human Homeobox A10 (HOXA10) genes are important because the dysregulation in some of these genes can lead to endometriosis." (PMID 36901685, 2023). "The HOXA10 methylation and expression levels have been identified to play a role in various pathways during the pathogenesis of endometriosis." (PMID 36979165, 2023). "All case-control studies compared the HOXA10 DNA methylation level between endometriosis and normal women." (PMID 36979165, 2023). "Identifying HOXA10 DNA methylation levels in women with endometriosis is also crucial as the base knowledge for developing site-specific DNA demethylation agents in endometriosis treatment." (PMID 36979165, 2023). "Based on the systematic review, HOXA10 is methylated in the endometrium of women with endometriosis during the secretory phase, and the methylation pattern is similar across populations." (PMID 36979165, 2023). "Apart from endometriosis, the promoter region of HOXA10 also was reported to be methylated in other diseases, such as endometrial cancer and gastric cancer." (PMID 36979165, 2023). "In baboon models of endometriosis, a significantly reduced endometrial expression of HOXA10 and integrin β3 (ITGB3), which are known to be involved in endometrial receptivity, has been reported one year after the induction of endometriosis." (PMID 36830705, 2023). "The last example is promoter hypermethylation of HOXA10 in eutopic endometrium from women with endometriosis." (PMID 36830705, 2023). "Our primary interest is mainly the aberrant hypermethylation of HOXA10 has been reported to play a role in endometriosis." (PMID 36979165, 2023). "Aberrant hypermethylation of HOXA10 has been reported to play a role in endometriosis and implantation failures in women receiving in vitro fertilization (IVF) treatment." (PMID 36979165, 2023). "In mice with apparently normal endometrium, endometrial expression of Hoxa10, Hoxa11 and Igfbp1 (Insulin-like growth factor binding protein-1) was significantly reduced 14 weeks after the induction of endometriosis." (PMID 36830705, 2023). "Letrozole also has been reported to gain the expression of HOXA10 in endometriosis and improve endometrial receptivity." (PMID 36979165, 2023). "This systematic review provides insight into the relationship between endometriosis and the expression of the HOXA10 gene." (PMID 37629050, 2023). "The down-regulation of HOXA10 triggers an autophagic function in endometriosis via the Wnt/b-catenin axis, b3-integrin, FK506 binding protein 4, beclin-I, and LC3-II." (PMID 36979165, 2023). "It has been shown that HOXA10 is aberrantly down-regulated in the endometrium of women with endometriosis during the secretory phase, which is partly due to HOXA10 promoter hypermethylation and gene-silencing." (PMID 37108154, 2023). "In endometriosis, HOXA10 has been proposed as one of the potential biomarkers for the diagnosis of endometriosis." (PMID 36979165, 2023). "The HOXA10 DNA methylation level was significantly higher in the endometrial tissue of the women with endometriosis." (PMID 36979165, 2023).